PLA2R1 (phospholipase A2 receptor 1)
Diseases named in the same sentence as PLA2R1 in open-access papers (continued):
Sharing a sentence is not in itself a finding about the gene and the disease.
breast cancer (continued). "Our goal was to study the level of PLA2R1 mRNA expression in different histological grades and molecular subtypes of breast cancer." (PMID 32751713, 2020). "PLA2R1 is involved in several vital biological process of breast cancer, which include triggering DNA damage, carcinogenesis, cell death and cell differentiation." (PMID 32751713, 2020). "We performed a bioinformatics analysis on the publicly available Cancer Cell Line Encyclopedia (CCLE) to assess PLA2R1 CpG island methylation in 44 breast cancer cell lines of different molecular subtypes." (PMID 32751713, 2020). "Taken together, these results imply that PLA2R1 promoter methylation outperformed PLA2R1 expression in discriminating breast cancer from benign fibroadenomas." (PMID 32751713, 2020). "Our findings revealed that PLA2R1 was differentially expressed among different histological grades and molecular subtypes of breast cancers compared to benign ones." (PMID 32751713, 2020). "We also assessed the degree of PLA2R1 promoter methylation in relation to the expression of PLA2R1 in human breast cancer tissues." (PMID 32751713, 2020). "Using qRT-PCR, we found that methylation of the PLA2R1 promoter was significantly elevated (fold change = 1.079, p < 0.0001) in breast cancer tissues when compared with the benign control." (PMID 32751713, 2020). "Growth-associated colony formation in soft agar was blocked in mammary cancer cell lines MDA-MB-231 and Cama-1 constitutively expressing PLA2R1." (PMID 30542512, 2018). "The collected data were compared with the corresponding findings in PLA2R1- and control-transfected breast cancer cell line MDA-MB-453 that was previously used to demonstrate the tumour-suppressive role of PLA2R1." (PMID 30542512, 2018). "PLA2R1 has been shown to be differentially expressed in normal and mammary cancer cells, and this expression is controlled by epigenetic mechanisms such as DNA methylation and histone modification." (PMID 28933369, 2017). "The phospholipase A2 receptor (PLA2R1) acts as a tumor suppressor in certain tumors including breast cancer." (PMID 28933369, 2017). "Nearly complete methylation of the analyzed PLA2R1 promoter region along with PLA2R1 gene silencing was identified in MDA-MB-453 mammary cancer cells." (PMID 26672991, 2015). "Similar to previous data obtained in leukemia cells, the analyzed PLA2R1 promoter region was nearly completely methylated in the mammary cancer cell line MDA-MB-453 where PLA2R1 gene was silenced." (PMID 26672991, 2015). "Contrary, knockdown of PLA2R1 increased the transformed phenotype of MDA-MB-436 breast cancer cells as measured by the increased size of soft agar colonies." (PMID 26672991, 2015). "It has recently been proposed that the M-type phospholipase A2 receptor (PLA2R1) acts as a tumour suppressor in certain malignancies including mammary cancer." (PMID 26672991, 2015). "These miRNAs should be further tested as putative regulators of PLA2R1 expression in mammary cancer cells." (PMID 26672991, 2015). "In MCF-7 and BT-474 mammary cancer cell lines, a higher DNA methylation degree and reduced PLA2R1 expression were found in comparison with those in normal HMEC." (PMID 26672991, 2015). "It has been demonstrated that upon knockdown of CENP-A and overexpression of PLA2R1, breast cancer cell proliferation and migration ability are restrained with enhanced apoptosis, whereas the tumor growth and volume were also effectively suppressed upon CENP-A knockdown in vivo." (PMID 39273649, 2024). "This detected hypermethylation of the PLA2R1 promoter may explain the downregulation of PLA2R1 mRNA expression in breast cancer tissues." (PMID 32751713, 2020). "Our results showed that PLA2R1 average promoter methylation was able to distinguish breast cancer from a benign control with the area under the curve (AUC) = 0.80 (p < 0.0001) and the sensitivity, specificity and cutoff point at 63%, 93% and 1.03, respectively." (PMID 32751713, 2020).
breast cancer (continued). "Our results suggest that breast cancer cells may use the hypermethylation of the PLA2R1 promoter to induce its downregulation as a defense mechanism against its tumor suppressive effects." (PMID 32751713, 2020). "More specifically, we wanted to assess the degree of PLA2R1 promoter methylation that may regulate the expression of PLA2R1 in human breast cancer tissues." (PMID 32751713, 2020). "We can also anticipate that PLA2R1 promoter methylation might serve as a potential therapeutic target in breast cancer." (PMID 32751713, 2020). "Therefore, it will be of interest for future studies to assess which cellular signalling pathways are activated by PLA2R1 and which physiological ligands trigger the PLA2R1 mediated signalling functions in mammary cancers." (PMID 26672991, 2015). "Some studies correlate the sPLA2 antitumor activity with the expression of the PLA2 receptor (PLA2R) in tumor cells and state that the ectopic expression of the PLA2R in PLA2R1-negative breast cancer cell lines strongly induces cancer cell death." (PMID 35432496, 2022). "Our findings confirmed that lower levels of PLA2R1 mRNA expression were detected in Grade II (fold change = 0.15) and Grade III (fold change = 0.028) breast cancer when compared to the benign control." (PMID 32751713, 2020). "A statistically significant hypermethylation of the PLA2R1 promoter was detected in both Grade II (fold change = 1.034, p < 0.0001) and Grade III (fold change = 1.279, p < 0.0001) breast cancers compared to benign breast tissues." (PMID 32751713, 2020). "Hypermethylation of the PLA2R1 promoter was detected in triple negative (HCC1395, HCC1187, DU4475, KPL1 and BT20) and HER2-positive (SKBR3, HCC202 and HCC1954) breast cancer cell lines." (PMID 32751713, 2020). "Based on the analysis of these datasets, we detected a significant decrease (p < 0.0001) in the mRNA level of PLA2R1 in Grade II and III in comparison to Grade I breast cancer." (PMID 32751713, 2020). "The observed PLA2R1 inhibitory effect in LNCaP and PC-3 cells on clonogenicity is consistent with data obtained in MDA-MB-231 breast cancer cells." (PMID 30542512, 2018). "To decipher the opposite effects of PLA2R1 in LNCaP and PC-3 cells together with those described in the breast cancer cell line MDA-MB-453, we validated our transfection method and experimental procedures by transfecting MDA-MB-453 cells to overexpress PLA2R1." (PMID 30542512, 2018). "MS-HRM analyses demonstrated differential PLA2R1 promoter methylations in HMEC and breast cancer cell lines." (PMID 26672991, 2015). "The purpose of this study was to examine expression of PLA2R1, degree of PLA2R1 promoter methylation, and expression of methylation regulating enzymes DNA-methyltransferases (DNMT) in normal and mammary cancers cell lines." (PMID 26672991, 2015). "Although we have not directly addressed the question of how PLA2R1 suppresses tumorigenesis in breast cancer, there are many possible mechanistic explanations that can be underlined." (PMID 32751713, 2020). "Our bioinformatics analysis from the bc-GenExMiner database demonstrated a lower expression of PLA2R1 mRNA in basal-like, human epidermal growth factor receptor 2 (HER2)-positive and luminal B breast cancers in comparison to both luminal A and normal breast-like cancers (p < 0.0001)." (PMID 32751713, 2020). "However, only the aggressive breast cancers—Grade III and the TNBC subtype—demonstrated statistically significant downregulation of PLA2R1 mRNA expression compared to benign control." (PMID 32751713, 2020). "PLA2R1 stimulated apoptosis mediating sPLA2-independent induction of the estrogen-related receptor α (ERRα) expression via JAK2/STAT5 signalling and mitochondrial ROS-production in MDA-MB-453 breast cancer cells." (PMID 30542512, 2018).
breast cancer (continued). "Furthermore, in mammary cancer cell lines MDA-MB-231 and Cama-1 the constitutive expression of PLA2R1 was found to block the colony growth in soft agar, supporting a tumour suppressive role of PLA2R1." (PMID 26672991, 2015). "Non-significant hypermethylation of PLA2R1 promoter was detected in HER2-positive (fold change= 1.033, p = 0.07), luminal A (fold change = 0.871, p = 0.5) and luminal B (fold change =1.03, p = 0.5) breast cancers." (PMID 32751713, 2020).
leukemia (6 papers, 2012 to 2025). A malignant (clonal) hematologic disorder, involving hematopoietic stem cells and characterized by the presence of primitive or atypical myeloid or lymphoid cells in the bone marrow and the blood. "A limited number of studies supported that PLA2R1 was a tumour suppressor, and its expression was reduced in many cancers such as blast cancer, and leukaemia." (PMID 41354645, 2025). "PLA2R1 methylation quantification by methylation-sensitive high-resolution melting analysis demonstrated a significantly higher methylation degree in adult leukaemia patients." (PMID 32493972, 2020). "We have recently detected PLA2R1 promoter hypermethylation in leukemic cell lines and leukocytes of patients with leukemia." (PMID 26672991, 2015). "MS-HRM analysis of the PLA2R1 locus in patients with different types of leukemia indicated an average methylation of 28.9% ± 17.8%, compared to less than 9% in control subjects." (PMID 23217014, 2012). "PLA2R1 expression was found decreased in leukaemia, mammary, renal and thyroid cancers." (PMID 26672991, 2015). "A further question arising from our study is whether the extent of PLA2R1 methylation can be used as a biomarker for stratifying patients for treatment of leukemia." (PMID 23217014, 2012). "The study shows for the first time that PLA2R1 gene sequences are a target of hypermethylation in leukemia, which may have pathophysiological relevance for disease evolution in MDS and leukemogenesis." (PMID 23217014, 2012). "The study also shows that the determination of PLA2R1 methylation by melt curve and MS-HRM analyses may be useful for risk stratification of MDS and AML patients and therapeutic control of leukemia using methylation inhibitors." (PMID 23217014, 2012). "In addition to diagnosis and control of methylation-related therapies the observation that inhibition of DNA methylation can restore the PLA2R1 expression may have important implications for development of novel strategies to treat leukemia." (PMID 23217014, 2012). "PLA2R1 methylation can be of special interest in patients lacking a common leukaemia subtype classification if no other molecular biomarkers are available." (PMID 32493972, 2020).
progeria (5 papers, 2018 to 2023). "We conclude that loss of Pla2r1 in a mouse model of progeria reduces bone alterations and signs of cellular senescence." (PMID 30216637, 2018). "The effect of ruxolitinib on progeria phenotypes is a phenocopy of that observed in Pla2r1 knockout mice, that is, reduced numbers of rib fractures, increased BMC, and improved grip strength." (PMID 32196928, 2020). "We found earlier that the targeting of the transmembrane protein PLA2R1 overcomes senescence and improves phenotypes in a mouse model of progeria." (PMID 32196928, 2020). "A knockout of Pla2r1 in a mouse model of progeria attenuates some premature-aging signs, such as rib fracture and decreased bone content, while simultaneously decreasing a senescence marker level." (PMID 32429546, 2020). "Another genetic intervention worth mentioning is the knockdown of the phospholipase A2 receptor (PLA2R1) in a mouse model of progeria." (PMID 31560163, 2019). "It is intriguing that, in a mouse model of progeria, deleting the phospholipase receptor PLA2R1 improved specific healthspan parameters." (PMID 31560163, 2019). "In progeria mice with premature aging, knockdown of Pla2r1 significantly decreases several different aging phenotypes." (PMID 31560163, 2019). "Whole‐body knockout of Pla2r1 in a mouse model of progeria decreased some premature aging phenotypes, such as rib fracture and decreased bone content, together with decreased senescence marker." (PMID 30216637, 2018). "Moreover, we recently observed that PLA2R1 contributes to progeria phenotypes in vitro in progerin‐expressing cells and in vivo in the Zmpste24−/− murine model of progeria." (PMID 32196928, 2020). "We previously showed that the phospholipase A2 receptor (PLA2R1) promotes senescence induced by replicative, oxidative, and oncogenic stress but its role during progerin‐induced senescence and in progeria is currently unknown." (PMID 30216637, 2018). "Pla2r1 is a well‐known pro‐senescent gene that fosters some age‐related phenotypes in COPD and progeria." (PMID 37667516, 2023). "The inflammatory marker IL‐8 and the senescence marker p21 were both reduced in bone mRNA in mice lacking Pla2r1 compared with control progeria mice." (PMID 31560163, 2019). "PLA2R1 is regulating the JAK/STAT signaling, but we do not yet know whether targeting this pathway directly would influence cellular and in vivo progeria phenotypes." (PMID 32196928, 2020).
asthma (4 papers, 2017 to 2023). "This study identified interactions between genetic variants near or within five genes, PLA2G4A, PLA2R1, RELA, PRKD1 and PRKCA, and occupational exposures to LMW agents or irritants for current adult-onset asthma." (PMID 27504716, 2017). "Overall, all these data suggest that any or all of these genes—PLA2G4A, PLA2R1, RELA, PRKD1, and PRKCA—may play a role in the risk of asthma in adults in association with exposure to LMW agents or irritants." (PMID 27504716, 2017).
gastric cancer (4 papers, 2017 to 2024). A primary or metastatic malignant neoplasm involving the stomach. "However, PLA2R1 regulation of tumour growth and progression remains contradictory as PLA2R1 was found expressed at higher levels in comparison to corresponding normal cells in pancreatic and gastric cancers, and in leukemic blasts of patients with acute myeloid and acute lymphoid leukaemia." (PMID 30542512, 2018). "The B cells, CD8 T cell, and dendritic cell infiltration scores of the PLA2R1 gene had no statistical significance in gastric cancer, while the infiltration scores of CD4 T cells and neutrophils were significant in gastric cancer, and macrophages were extremely significant." (PMID 36140749, 2022).
kidney cancer (4 papers, 2018 to 2024). Primary or metastatic malignant neoplasm involving the kidney. "Previous studies have also demonstrated that the downregulation of PLA2R1 is related to thyroid, breast, and kidney cancers." (PMID 36106120, 2022).
prostate carcinoma (4 papers, 2018 to 2020). A carcinoma that arises from epithelial cells of the prostate gland. "Accordingly, PLA2R1-knockdown decreased cell viability/proliferation and wound healing, but increased susceptibility to apoptotic stimuli highlighting possible pro-oncogenic PLA2R1 effects in prostate cancer cells in vitro." (PMID 30542512, 2018). "We previously provided evidence of PLA2R1’s tumour-suppressive role in solid tumours investigating the prostate cancer cell line LNCaP in in vivo xenograft models." (PMID 32493972, 2020). "An increased expression of PLA2R1 was also demonstrated in ovarian carcinoma effusions, dermatofibrosarcoma, and human prostate cancer cell line PC-3, contradicting an exclusive function of PLA2R1 as tumour-suppressor." (PMID 30542512, 2018). "Comparing to PrEC cells, the PLA2R1 mRNA level was significantly upregulated in androgen-insensitive PC-3 prostate cancer cells." (PMID 30542512, 2018). "As gene target, we analysed a specific PLA2R1 sequence that we identified to be hypermethylated in leukaemia and prostate cancer cells." (PMID 30546833, 2018). "However, this was clearly at odds with the observations of another study that reported significant upregulation of PLA2R1 in prostate cancer when compared to normal tissues." (PMID 32751713, 2020). "Therefore, the aim of the present study was to address the growth-related and cell specific role of PLA2R1 in prostate cancer cell lines LNCaP and PC-3 that differ in protein expression profiles." (PMID 30542512, 2018). "We attempted to exclude methodology-associated errors (genotypic artefacts or cross contaminations) that might be involved as potential confounding factors in diversification of PLA2R1 expression in the analysed prostate cancer cell lines by short tandem repeat analysis." (PMID 30542512, 2018). "We did not detect any PLA2R1 mRNA expression in androgen-sensitive LNCaP prostate cancer cells." (PMID 30542512, 2018).
steatosis (3 papers, 2023 to 2025). Increased lipid within the cytoplasm of cells. "We next explored the role of PLA2R1 in steatosis, one of the main liver alterations associated with NAFLD development." (PMID 37667516, 2023). "ALT > 40 U/L (OR: 3.00, 95% CI:1.35–6.67, p = 0.007) and PLA2R1 rs3749117 were independent predictors of moderate-severe steatosis." (PMID 38836837, 2024). "Fibrosis and steatosis were low in old WT mice; the impact of Pla2r1 KO was more difficult to evaluate, even though a slight decrease in both was observed." (PMID 37667516, 2023). "Consistently, H&E staining of the livers confirmed that Pla2r1 KO mice displayed less severe forms of steatosis, and Oil Red O staining of the lipid droplets highlighted the reduction of lipid accumulation in the liver of these mice compared with WT mice." (PMID 37667516, 2023). "Supporting this protective role, experimental studies demonstrate that hepatocyte-specific deletion of PLA2R1 in mice exacerbates diet-induced metabolic dysfunction, inflammation, and steatosis, confirming its function as a guardian of hepatocyte metabolic health under lipotoxic stress." (PMID 41497980, 2025). "After multivariate adjustments, IR (OR: 3.80, 95% CI: 1.22–6.83, p = 0.021) and PLA2R1 rs35771982 (OR: 3.24, 95% CI: 1.96–6.22, p = 0.038) remained significantly associated with nonobese moderate-severe steatosis." (PMID 38836837, 2024). "Our results identify a potential role for Pla2r1 in promoting several of the alterations associated with NASH including cellular senescence, steatosis, and fibrosis and generating a histopathological score compiling steatosis, ballooning, and fibrosis further supports the findings." (PMID 37667516, 2023). "Moreover, these Pla2r1 KO mice were partially protected from diet‐induced senescent cell accumulation, steatosis, and fibrosis." (PMID 37667516, 2023). "The presence of moderate-to-severe steatosis in nonobese MASLD may be associated with the effects of PLA2R1 rs35771982, whereas rs3749117 mutations may have pronounced effects on moderate-to-severe steatosis in obese MASLD patients." (PMID 38836837, 2024). "For liver steatosis, the CERS4 rs17160348 TT genotype, PLA2R1 rs3749117 CC genotype, and PLA2R1 rs3749117 CC genotype had significantly higher steatosis proportions than the other 2 genotypes, respectively, while PON1 rs854560 TT genotype had the lower steatosis proportion than the wild genotype." (PMID 38836837, 2024). "Mutations in PLA2R1 rs35771982 and CERS4 rs17160348 are associated with susceptibility to MASLD in nonobese individuals, while PLA2R1 rs35771982 mutation is a risk factor for moderate-to-severe steatosis and steatohepatitis in nonobese patients." (PMID 38836837, 2024).